LIFR (LIF receptor subunit alpha)
Diseases named in the same sentence as LIFR in open-access papers (continued):
Sharing a sentence is not in itself a finding about the gene and the disease.
cancer (continued). "Our results from the analysis of cancer cell lines as well as the meta-analysis of public DNA methylome data unambiguously showed increased methylation levels at the LIFR gene promoter in colorn cancer samples compared to other types of cancers and normal colon samples." (PMID 28751909, 2017). "In addition to its ability to suppress the expression of E-cadherin, miR-9 also promotes carcinoma invasion and metastasis by targeting the leukemia inhibitory factor receptor (LIFR), leading to the inactivation of prometastatic signals mediated by the Hippo-YAP pathway." (PMID 25717380, 2014). "A novel LIFR inhibitor, EC359, resulted in the induction of apoptosis and reduced the levels of cancer stem cell markers SOX2, OCT4, and NANOG in EC." (PMID 40804837, 2025). "Present findings ground the basis for exploiting LIFR antagonists in the treatment of FGFR4-related conditions overcoming limits and side effects of pan-FGFR inhibitors in cancer treatment." (PMID 37945798, 2024). "A prognostic role of LIFR and its ligand (LIF) has been recognized across several human cancers, but the importance of this pathway and its co-occurrence with a JAK1 mutation have never been explored in lymphoid malignancies." (PMID 37287455, 2023). "Although other IL-6 family members have been shown to regulate the metastasis of multiple cancer types, the role of LIF and LIFR remains challenging to access." (PMID 36925915, 2023). "Leukemia inhibitory factor receptor (LIFR) and its ligand LIF play a major role in cancer progression, metastasis, stemness, and therapy resistance." (PMID 34400617, 2021). "Editing at the fifth position of the mature miR-200b-3p impairs the ability to inhibit ZEB1/ZEB2 and acquires a new target-leukemia inhibitory factor receptor (LIFR)-conferring a net effect of increasing motility and invasion in a series of cancer cell lines." (PMID 33430133, 2021). "Although other members of the IL-6 family have been shown to be involved in the metastasis of multiple types of cancer, the role of LIF and LIFR has been challenging to determine." (PMID 34395259, 2021). "Edited miR-200b failed to inhibit EMT regulator ZEB1/ZEB2 and acquired new ability to repress a new group of targets such as leukemia inhibitory factor receptor (LIFR), promoting cell migration and invasion in a variety of cancer types." (PMID 32209098, 2020). "Leukemia inhibitory factor (LIF) regulates several features of cancers and cancer stem cells (CSCs) through binding to LIF receptor (LIFR)." (PMID 32651426, 2020). "Since LIF supplementation and activation of LIF/LIFR signalling in the GC context seems to be beneficial in terms of CSC targetting, its capacity as a GC cancer biomarker was pondered." (PMID 32707998, 2020). "The central gene is PIK3R1 in Module 0, which module contains eight DEGs related to classical cancer pathways (FCER1A, GNG11, IGF1, LIFR, PDK4, PIK3R1, RCAN2, and UGCG)." (PMID 31119098, 2019). "Several current partially successful approaches for cancer therapy are in agreement with the i-CSC/p-ESC model, targeting crucial factors common to embryos and tumors, such as HSP70, HLA-G, ID, LIF/LIFr, and CD44." (PMID 30899759, 2019). "Network analysis indicates that DDX5, LIFR, ZEB2, mir-21, mir-27b, mir-30a, mir-141, mir-182 and mir-200c were shared across different constructed networks, indicting their crucial role in cancer biology and progression, which has been reported previously." (PMID 24796549, 2014). "In contrast, DCN (chr12q21.33), LIFR (chr5p13.1), ABCA8 (chr17q24.2), C7 (chr5p13.1) and ZEB2 (chr2q22.3) on predicted PCSRs were down-expressed in 9, 7, 8, 8 and 8 cancers, respectively." (PMID 24796549, 2014). "Many of the genes, identified in this study as the potential targets of differentially regulated miRNAs are known to be involved in cancer through their effects on cell differentiation (CDK6, LIFR), apoptosis (PIM1) or hematopoiesis (GATA2, TAL1)." (PMID 20459673, 2010).
cancer (continued). "Another strategy is using the LIFR inhibitor EC359, which diminishes the stemness of cancer cells." (PMID 40804837, 2025). "We summarize the role of a breast cancer suppressor receptor (LIFR, CD118), part of the leukemia inhibitory factor (LIF, IL-6 family), which is inhibited in bone under low oxygen tensions and exhibits distinct influences in other cancers." (PMID 40977686, 2025). "LIF is a highly pleiotropic member of the IL-6 family of cytokines, upon binding to the LIFR complex promotes the crosstalk between the extracellular matrix (ECM) and cancer cells and mediates the transition through a pro-invasive phenotype of stromal fibroblasts and cancer cells." (PMID 37945798, 2024). "The heatmap showed that the 15 CpG sites (located on B3GALNT1, C6orf97, FAM72A, FAM72B, LIFR, OSMR, ZNF264, and ZNF543) well‐distinguished CRC from adjacent normal tissues, WBCs, and 28 other types of cancer in TCGA, as well as 23 other types of cancer in GEO." (PMID 37649326, 2023). "Although increasing numbers of studies are revealing an indispensable critical role of LIFR in tumorigenesis for various different cancers, no systematic analysis of LIFR has appeared thus far." (PMID 36925915, 2023). "​To determine whether LIFR is a functional gene in UCEC cells, we estimated cancer cell migrative and invasive abilities by Trans-well migration/invasion assays." (PMID 36925915, 2023). "Since previous studies have shown that challenging cancer cells with LIF promotes their proliferation and the epithelial-to-mesenchymal transition (EMT), we functionally assessed whether LIFR inhibition reverses this pattern." (PMID 36359879, 2022). "LIFR and its major ligand LIF belong to the interleukin-6 (IL-6) cytokine family and have a central role in immune system regulation, carcinogenesis, and dissemination in several human cancers." (PMID 35847866, 2022). "Several tumors exhibit upregulated JAK/STAT, ERK/MAPK, and PI3K/AKT signaling via autocrine or paracrine activation of LIF/LIFR GP130, and this pathway significantly contributes to EMT in several cancers, disease progression, and a poorer relapse-free survival in several cancers." (PMID 35847866, 2022). "Generally speaking, cancer stem cell maintenance by LIF and LIFR seem to follow a similar trend as that seen in mESCs: LIF signaling leads to the activation of STAT3, which increases the stem cell like properties in solid tumors through transcriptional regulators." (PMID 34395259, 2021). "The direction of the altered expression of LIFR, ARHGAP24, and CNTNAP2 varied in each cancer type." (PMID 33463006, 2021). "They further demonstrate that this engineered LIFR exhibits improved affinity relative to the wild-type receptor, leading to better disruption of LIF signaling in cancer cells, and highlighting promise of such ligand traps as therapeutic strategy for cancer treatment." (PMID 33846527, 2021). "LIF/LIFR signalisation effect in cancer remains contradictory, with either negative or positive regulation of cancer cell properties depending on cancer types and studies." (PMID 32707998, 2020). "Many studies have reported LIFR differential expression in the cancer context compared with non-tumoral conditions." (PMID 32707998, 2020). "We first identified LIFR, PIK3R1, and MMP12 as novel prognostic biomarkers in this cancer." (PMID 31119098, 2019). "The process requires some crucial interacting factors, such as LIF/LIFr, IL6/IL6r, IL10, IL11, GP130, JAK, and STAT3, and correlated signal pathways, leading to the switch from anchorage-independent to anchorage-dependent growth, both in embryos and cancer." (PMID 30899759, 2019). "In cLIF cancer cells, the LIFR level was constitutively high, indicating they were not responsive to exogenous LIF stimulation." (PMID 30504771, 2018). "However, LIFR does not always act as a suppressor in carcinogenetic processes, and its function in each type of cancer should be examined through targeted research." (PMID 36925915, 2023).
cancer (continued). "In addition, by using in vitro cancer cells and pharmacological approaches, we demonstrate that inhibition of LIF/LIFR signaling might have utility in the treatment of GC." (PMID 35847866, 2022). "The results from the CCLE support that the selected genes C20orf194 and ZNF304 (LIFR without data) were specifically hypermethylated and downregulated in CRC cell lines compared to those of other cancer types." (PMID 35974349, 2022).
skeletal dysplasia (5 papers, 2007 to 2025). Any Mendelian diseases that affects growth and development of the skeleton. "This included seven genes (LIFR, TMEM38B, PLS3, NANS, SLC26A2, ALX4, and PLS3) associated with skeletal dysplasia or bone disease, and four of them were ARE-containing genes with increased expression." (PMID 29727687, 2018). "Mutations in the genes encoding some of the molecules in these pathways, including RPS6SKA3, LIFR, TNFRSF11A and IKBKG, have been associated with human skeletal dysplasias, again suggesting that the remaining genes may also serve critical roles in endochondral ossification." (PMID 17565682, 2007).
cardiovascular disease (3 papers, 2021 to 2023). "Given the imbalance in research studies between interleukin-6 and the other members of the IL-6 cytokine family, it is time to reconsider the involvement of the OSMR/gp130 as well as the LIFR/gp130 complexes in human cardiovascular diseases." (PMID 35163735, 2022). "We investigated the impact of common genetic variants in OSM and its receptors, OSMR and LIFR, on overall plaque vulnerability, plaque phenotype, intraplaque OSMR and LIFR expression, coronary artery calcification burden and cardiovascular disease susceptibility." (PMID 33959646, 2021). "However, the OSM-OSMR/LIFR pathway is unlikely to be causally involved in lifetime cardiovascular disease susceptibility." (PMID 33959646, 2021). "However, the OSM-OSMR/LIFR pathway is unlikely to be causally involved in lifetime cardiovascular disease susceptibility as none of the investigated eQTLs associated with cardiovascular diseases." (PMID 33959646, 2021).
infection (3 papers, 2011 to 2020). The state of being infected such as from the introduction of a foreign agent such as serum, vaccine, antigenic substance or organism. "Significant reduction of LIF, LIF receptor (LIFR) and pSTAT3 was observed in endometrium of patients with dormant genital tuberculosis, suggesting a possibility that this infection could be one of reasons leading to RIF." (PMID 27304912, 2016).
adenocarcinoma (2 papers, 2022 to 2025). A common cancer characterized by the presence of malignant glandular cells. "Indeed, expression of LIFR is increased in t-NEPC as compared to adenocarcinoma and correlates with elevated NE marker expression in patients’ tissues." (PMID 35109899, 2022). "However, SUCLG2 expression has been found to be not significantly different between t-NEPC and high-grade adenocarcinoma patients, indicating that LIFR activation and STAT3 signaling are not exclusive regulators of SUCLG2 in t-NEPC." (PMID 35109899, 2022).
neurodegenerative disease (1 paper, 2024). A disorder of the central nervous system characterized by gradual and progressive loss of neural tissue and neurologic function. "In conclusion, LIFR levels and signaling have complex connections with various aspects of neuronal function and are associated with a wide range of neuropsychiatric and neurodegenerative diseases." (PMID 38819224, 2024). "LIFR-mediated signaling can affect neuroprotective pathways, and its dysregulation may contribute to the progression of neurodegenerative diseases." (PMID 38819224, 2024).
LIFR also shares sentences with these, for which no sentence is quoted: endometriosis (5 papers); dysplastic nevi (3); metastatic melanoma (3); nevus (3); diabetes (2); gallbladder cancer (2); multiple sclerosis (2); pancreatic adenocarcinoma (2); schizophrenia (2); viral infection (2); achondroplasia (1); acute graft versus host disease (1); acute myeloid leukemia (1); adenoma (1); age (1); Arthritis (1); B-cell lymphopenia (1); bipolar disorder (1); cancers of digestive system (1); cervical cancer (1); Chlamydia infection (1); chronic GvHD (1); Chronic myeloid leukemia (1); chronic pancreatitis (1); CNS tumors (1); colitis (1); colon adenocarcinoma (1); colorectal (1); cryptorchidism (1); experimental autoimmune encephalomyelitis (1).
A further 33 diseases each share a sentence with LIFR in 1 paper.